CRP (C-reactive protein)
Diseases named in the same sentence as CRP in open-access papers (continued):
Sharing a sentence is not in itself a finding about the gene and the disease.
COVID-19 (continued). "Also, comparing the two groups of COVID-19 and control in terms of ACE2, the CRP level was found to be significantly higher in carriers of TT genotype, which is positively correlated with COVID-19 susceptibility." (PMID 36134024, 2022). "Authors concluded that high levels of CRP are associated with COVID-19 severity." (PMID 35458497, 2022). "Cut-off values and ORs (95% CI) for the risk of developing severe/critical COVID-19 in the univariate and multivariate analyses for News-2, Ferritin, CRP and NLR (model 1), for the cytokines sCD25, IL1Ra and IL18 (model 2) and for activated CD4 and CD8, NK, Tc2 and EMRA CD8 (model 3)." (PMID 35425776, 2022). "Age, oxygen saturation, C-reactive protein levels and creatinine levels were used to estimate the in-hospital mortality risk for COVID-19 patients in a point based score: 1 point per age decade, 4 points for oxygen saturation <92%, 8 points for CRP > 10 mg/l and 4 points for creatinine > 84 μmol/l." (PMID 36304183, 2022). "Elevated CRP was associated with an increased mortality risk after recovery from COVID-19." (PMID 35646997, 2022). "Similarly, a meta-analysis considering data for 10,491 confirmed COVID-19 patients concluded that elevated CRP and LDH levels were independently associated with increased risk of poor outcomes." (PMID 35893707, 2022). "Furthermore, the prognostic value of the CRP/prealbumin for predicting mortality in COVID-19 is significantly greater than the traditional risk factor, CRP." (PMID 35807907, 2022). "Additionally, we found an indirect path between EMO and teachers’ perception about the impact of COVID-19 through teachers’ perception of risk of contracting SARS-CoV-2 (CRP) and perception of the effectiveness of health measures (PEHM) (β = 0.03; p < 0.001)." (PMID 36141916, 2022). "In addition, a higher mean age, temperature, pulse and higher CRP level were significantly associated with severe to critical cases of COVID-19." (PMID 35820935, 2022). "A retrospective multicenter study of 68 COVID-19 noted 27 deaths that could be attributed to myocardial damage and/or circulatory failure as one of the primary causes of mortality, with elevated C-reactive protein and IL-6 levels linked to higher mortality." (PMID 35336888, 2022). "Many studies have identified clinical characteristics as risk factors associated with severe COVID-19, which include aging, male gender, comorbidities, high D-dimer, C-reactive protein (CRP), lactate dehydrogenase (LDH), and white blood cells (WBCs) levels and low lymphocyte levels." (PMID 35600840, 2022). "CRP and IL-6 are also elevated in COVID-19 and are associated with worse prognosis." (PMID 38566903, 2022). "A positive association between CRP level and the severity of COVID-19 has been reported." (PMID 36518574, 2022). "Studies of CRP levels in association with COVID-19 in Africa appear to be rare, but the metabolic marker may not be rare." (PMID 35256885, 2022). "Finally, elevated CRP is a key marker of disease progression and a risk factor for mortality in COVID-19 patients, and it is indicative of developing a cytokine storm in COVID-19 patients." (PMID 36560453, 2022). "In fact, patients with MR-proADM level higher than the cut-off value of 1105 nmol/L show an increase of mortality of almost three times (OR 2.97, IC 1.7–5.28); also, CRP levels were independently associated with a higher risk of in-hospital mortality in COVID-19 patients (OR 2.85, IC 1.73–4.69)." (PMID 36010321, 2022). "Additionally, we found an indirect path between EMO and teachers’ perception about the impact of COVID-19 through teachers’ perception of risk of contracting SARS-CoV-2 (CRP) and perception of the effectiveness of health measures (PEHM) (β = 0.02; p < 0.001)." (PMID 36141916, 2022).
COVID-19 (continued). "However, our findings contradict other studies in the literature, in which it was reported that high D-dimer, fibrinogen and CRP levels increased the risk of stroke, in patients with concurrent COVID-19 and acute ischemic CVD." (PMID 35476075, 2022). "This makes pathophysiologic sense in acute COVID-19, as male sex at birth is linked to elevated basal levels of those proinflammatory cytokines (IL-6, CRP), coagulation factors, and complement components implicated in the hypercoagulable and proinflammatory state of acute SARS-CoV-2 infection." (PMID 35912863, 2022). "Similarly, other studies showed that a low level of vitamin A in plasma is significantly linked with increased inflammatory markers (CRP, ferritin) that lead to a higher risk of mortality among COVID-19 hospitalized patients." (PMID 35746548, 2022). "A strength of this research is that it provides scientific evidence indicating that comorbidities such as obesity, T2DM, and hypertension, as well as elevated levels of glucose, IL-6, LDH and CRP are associated with the COVID-19 severity among ICU-admitted patients." (PMID 35464048, 2022). "Extremely high CRP levels in COVID-19 patients are directly linked to poor prognosis." (PMID 35381033, 2022). "Furthermore, raised CRP level has also been found to be independently associated with acute renal failure in COVID-19 patients." (PMID 35836717, 2022). "In conclusion we propose a simple risk stratification score based on age, oxygen saturation (as an indicator for severity of pneumonia), creatinine and C-reactive protein, to differentiate between patients with high and low mortality risk from COVID-19 when admitted to the hospital." (PMID 36304183, 2022). "Moreover, it has been shown that elevated CRP levels in COVID-19 patients is strongly associated with Venous thromboembolism, acute kidney injury, critical illness, and mortality." (PMID 35794133, 2022). "Age, CRP, and D-dimer were linked with severity in COVID-19 patients." (PMID 36010198, 2022). "Model 1 tries to verify the indirect path between TS, JS, SE, EMO and teachers’ perception of COVID-19’s impact through teachers’ risk perception of contracting SARS-CoV-2 (CRP) and perception of the effectiveness of health measures (PEHM) on teaching methods (ITM)." (PMID 36141916, 2022). "Higher CRP levels in COVID-19 pediatric patients are significantly associated with neurological complaints since CRP is an inexpensive, widely available test, so it can be used in COVID-19 pediatric patients for early recognition of neurological presentations to treat patients early and adequately." (PMID 36420294, 2022). "Since COVID-19 disease could be associated with increased ESR and CRP levels, identification of surgical site infection in patients with COVID-19 could be challenging." (PMID 35042507, 2022). "Further evidence has linked CRP with adverse oral health and increased COVID-19 severity." (PMID 35208609, 2022). "Therefore, it appears CRP is useful in predicting VTE in the context of COVID-19, with D-dimer further improving risk assessment, however larger prospective studies are required to confirm the association." (PMID 36177015, 2022). "The analysis of clinical and laboratory parameters upon admission revealed that patients with diabetes, CRP above 19.5 mg/dL and elevated ferritin levels were independently associated with mortality secondary to COVID-19 (p = 0.013, p < 0.0001 and p = 0.029, respectively)." (PMID 35453779, 2022). "Patients developing severe forms of COVID-19 generally show strong systemic inflammation associated with increased cytokine release, as suggested by elevated concentration of interleukin (IL)-6, C-reactive protein (CRP), D-dimer, and ferritin." (PMID 35214651, 2022).
COVID-19 (continued). "Elevated CRP levels in the early stages of COVID-19 have been associated with more severe disease and greater mortality, leading to recommendation for its use as a prognostic indicator when evaluating risk in patients hospitalized for COVID-19." (PMID 35336888, 2022). "Furthermore, other studies have shown that receiving ivermectin as part of COVID-19 treatment is associated with a lower mortality rate, accompanied by lower levels of inflammatory biomarkers, such as C-reactive protein, ferritin, and D-dimer." (PMID 36482326, 2022). "The severity and the prolonged course of COVID-19 in these patients might be caused by persisting systemic inflammation reflected in fever and elevated C-reactive protein (CRP) as well as interleukin-6 (IL-6)." (PMID 33500431, 2021). "While moderate CRP elevation in the 3–10 mg/L range is useful in cardiovascular risk prediction, CRP values in COVID-19 may exceed 40 mg/L, reflecting an acute inflammatory response unrelated to the heart." (PMID 34441038, 2021). "In addition, hypercoagulation and vascular damage have been reported to be involved in the pathogenesis of COVID-19, and thrombosis and elevated inflammatory response with CRP have been reported to be associated with worsening of symptoms." (PMID 34697570, 2021). "A longitudinal cohort study with time-series design to estimate the spectrum of biochemical dataset suggests two other biochemical markers, C-reactive protein (CRP) and urea nitrogen, are associated with the risk of COVID-19-related acute respiratory failure and death." (PMID 34593760, 2021). "We propose that CRP-led algorithms may provide a cost-effective means to deploy PCT in the care of COVID-19 patients, removing the costs associated with redundant testing for this biomarker." (PMID 34859223, 2021). "Here, we evaluated whether a cumulative assessment of biomarkers such as CRP and D-dimer levels at admission and their dynamics would provide prognostic information for risk stratification in COVID-19 patients with pre-existing CVD." (PMID 34300252, 2021). "Moreover, adiposity is associated with higher levels of local and systemic inflammation markers, such as interleukin-6 and C-reactive protein, which have been positively correlated with COVID-19 susceptibility and severity." (PMID 34959805, 2021). "The association of higher CRP with worse outcomes may be due to the severity of the disease consistent with the ‘cytokine storm’ theory of COVID-19, where the innate immune system is activated releasing TNF-alpha, IL-6 and IL-1." (PMID 33683344, 2021). "Moreover, CRP status is also directly linked with the width of lung lesions and the severity of clinical symptoms of the COVID-19 patients." (PMID 34123639, 2021). "By univariate analysis, age, previous VTE, sPESI score, creatinine, platelets, leukocytes, CRP, fibrinogen (all values at peak during hospitalization), LA, and COVID-19 were significantly associated with the occurrence of transfer to the ICU in the study population." (PMID 34064556, 2021). "In a metaanalysis for acute phase reactants related to COVID-19 revealed that elevated serum CRP was associated with an increased some poor outcome [RR 1.84 (1.45, 2.33), P < 0.001; I2: 96%, P < 0.001] like severity of disease or need for intensive care unit, but not mortality." (PMID 33315349, 2021). "Despite these limitations, the association between elevations in N/L and CRP and need for mechanical ventilation reflect hypothesis generation that may warrant further exploration in solid organ transplant patients with COVID-19." (PMID 33034239, 2021). "Age >60 years and raised C-reactive protein (CRP) were also associated with COVID-19 death." (PMID 34400804, 2021). "A high CRP level is not only a key biomarker of disease progression and severity in patients with COVID-19 but is also a risk factor for death in patients with severe COVID-19 and is indicative of cytokine storm syndrome in patients with COVID-19." (PMID 34900028, 2021).
COVID-19 (continued). "However, extreme elevations of CRP are strongly associated with critical illness and mortality in COVID-19." (PMID 34567235, 2021). "Finally, one clinical characteristic (chest distress) and five laboratory findings (IL-6, TNI, PCT, CRP, Ca) were identified as the most predictive risk factors for prognostic prediction of severity for patients with moderate COVID-19." (PMID 33390780, 2021). "Furthermore, C-reactive protein was associated with a significant risk of critical illness in a study of 5279 patients with laboratory-confirmed COVID-19." (PMID 33534723, 2021). "Serum levels of CRP are also a risk factor of AKI in COVID-19 patients." (PMID 33907513, 2021). "In addition to COVID-19 associated coagulopathy, a parallel rise in CRP levels was observed in severely ill patients." (PMID 34262116, 2021). "Impaired spermatogenesis and increased apoptotic cells may be attributable to COVID-19-induced histone modifications associated with elevated CRP and fever that perturbed the optimum testicular temperature (2 – 4 0C below the average body temperature)." (PMID 34691068, 2021). "This review is aimed to highlight the current and most recent studies with regard to the clinical significance of CRP in severe COVID-19 and other viral associated illnesses, including update advances on the implication of CRP and its form specifically on the pathogenesis of these diseases." (PMID 34447386, 2021). "In addition, the use of a complex of B vitamins led to a decrease in the level of Hcy in COVID-19 patients; this was associated with a decrease in the period of fever and normalization of the level of D-dimer and C-reactive protein (CRP)." (PMID 34956420, 2021). "The objective of the study was to develop and validate a prediction model that identifies COVID-19 patients at risk of requiring oxygen support based on five parameters: C-reactive protein (CRP), hypertension, age, and neutrophil and lymphocyte counts (CHANeL)." (PMID 34158545, 2021). "Higher CRP levels are also linked to development of acute respiratory distress syndrome, higher troponin-T levels, and myocardial injury, which is observed in patients with severe COVID-19." (PMID 33633875, 2021). "Likewise, in our study, a high CRP/Alb ratio was closely related to disease severity and progression and was an independent risk factor for disease progression in patients with severe COVID-19." (PMID 34900028, 2021). "Several biomarkers such as D-dimer, CRP, ferritin, peripheral blood lymphocyte number, and neutrophil-to-lymphocyte ratio are associated with the severity and clinical outcomes in cohort studies of COVID-19, and routinely examined in hospitals." (PMID 34631752, 2021). "There is a need for simple tests to aid clinical management, as the behaviour of CRP in COVID-19 may provide useful immediate risk stratification as to who may have a poor outcome." (PMID 33683344, 2021). "However, laboratory parameters associated with COVID-19 such as CRP, IL-6, and BUN were also used in a few studies." (PMID 34367265, 2021). "Similarly, low baseline total and free testosterone in 31 COVID-19 patients recovered from ARDS in Italy are negatively correlated with inflammatory risk factors (ferritin, CRP procalcitonine, and D-dimer) and linked to COVID-19 severity." (PMID 34568081, 2021). "The CRP/Alb ratio can predict the risk of progression to critical disease or death early, providing a promising prognostic biomarker for risk stratification and clinical management of patients with severe COVID-19." (PMID 34900028, 2021). "A study conducted in three hospitals in China, with obese patients and non-obese controls, showed that obese patients were admitted to hospital with high C-reactive protein and low lymphocytes compared to controls, leading to a longer hospital stay and a three times higher risk of severe COVID-19." (PMID 34663823, 2021).
COVID-19 (continued). "According to our multivariable model, CRP ≥ 96.8 mg/L and a Shannon diversity index < 2.25 were associated with higher severity (a score of 6 or more in the COVID-19 WHO Clinical Progression Scale), suggesting that these patients’ variables are predictors of severe COVID-19." (PMID 34349747, 2021). "A large proportion of our patients (85.5%) received tocilizumab (anti-interleukin-6 receptor) according to our hospital protocol treatment for COVID-19 patients (pneumonia with bilateral involvement associated with elevated interleukin-6 and C-reactive protein, requiring oxygen therapy)." (PMID 34068847, 2021). "In this study, CRP is one of the risk factors for a fatal outcome in COVID-19 patients." (PMID 33546639, 2021). "Additionally, the occurrence of cytokine storms has been associated with critically ill COVID-19 patients, resulting in elevated levels of interleukin 6 and C-reactive protein; both have been associated with increased risk of stroke." (PMID 34574386, 2021). "A survey of antibiotic prescribing conducted in Scotland across 15 hospitals showed that a raised CRP ≥ 100 mg/L was associated with higher odds of antibiotic therapy in COVID-19 patients, implying a reliance on CRP in guiding treatment when bacterial infection was suspected." (PMID 34827363, 2021). "Taking together, the previous studies support our findings and thus we report that CRP and myoglobin could prove efficient prognostic biomarkers for COVID-19 associated mortality." (PMID 33727641, 2021). "To understand whether there were differences in plasma CRP levels underlying the grade of COVID-19, we stratified PC patients as moderate or severe according to the hospitalization where they needed oxygen therapy." (PMID 34944747, 2021). "Several studies have found that CRP levels were associated with COVID-19 severity." (PMID 33853568, 2021). "C-reactive protein (CRP) and D-dimer levels are associated with COVID-19 severity and prognosis." (PMID 34471180, 2021). "CRP is associated with CVD in COVID-19, but lacks clinical studies to support the notion that the common variation in CRP gene might have an alternative impact on the CVD." (PMID 34447386, 2021). "More recently, high CRP and low albumin have been associated with increased mortality in COVID-19." (PMID 34123422, 2021). "An elevated level of CRP may be an early marker to predict disease progression in patients with moderate COVID-19, and might help clinicians in identifying patients at risk for progression." (PMID 35076497, 2021). "As the first line of innate host defences for clearance ofviral infections, CRP might be linked to the overproduction of inflammatory cytokines in severe patients and may lead to dysfunction of various organ systems in COVID-19-infected patients." (PMID 35539890, 2021). "Our aim was to explore whether there was potential for an effective triage strategy, based on the CRP result, to distinguish COVID-19 patients with an increased risk of hospitalization." (PMID 35011944, 2021). "In a series of 91 consecutive COVID-19 adult patients with various comorbidities, we were able to collect a range of phenotypical (BMI, weight loss) and biological (albumin, CRP) data at the beginning of hospitalization for COVID-19 and one month after hospital discharge." (PMID 34209229, 2021). "Moreover, elevated IL-6 and CRP level and lymphopenia were found to be positively associated with disease severity and prognosis of patients with COVID-19." (PMID 33746189, 2021). "Low lymphocyte count and serum levels of C-reactive protein (CRP), D-dimer, ferritin, cardiac troponin, and IL-6 may be used in risk stratification to predict severe and fatal COVID-19 in hospitalized patients." (PMID 33946479, 2021).